GNE (glucosamine (UDP-N-acetyl)-2-epimerase/N-acetylmannosamine kinase)
Description:
Bifunctional enzyme that possesses both UDP-N-acetylglucosamine 2-epimerase and N-acetylmannosamine kinase activities, and serves as the initiator of the biosynthetic pathway leading to the production of N-acetylneuraminic acid (NeuAc), a critical precursor in the synthesis of sialic acids. By catalyzing this pivotal and rate-limiting step in sialic acid biosynthesis, this enzyme assumes a pivotal role in governing the regulation of cell surface sialylation, playing a role in embryonic angiogenesis. Sialic acids represent a category of negatively charged sugars that reside on the surface of cells as terminal components of glycoconjugates and mediate important functions in various cellular processes, including cell adhesion, signal transduction, and cellular recognition.
Synonyms: GLCNE; IBM2; Uae1; DMRV; NM; THC12
Tractability: Small molecule: a structure with a bound ligand is known; it has a high-quality binding pocket. PROTAC: ubiquitination databases record sites on it; its protein half-life has been measured.
Target class: Enzyme; Transferase
Gene: Protein-coding gene on chromosome 9 (36,214,441 to 36,277,042, reverse strand). Ensembl gene ENSG00000159921.
Subcellular location: Cytoplasm, cytosol
Subcellular location (Human Protein Atlas): Cytosol
Pathways (Reactome):
Disease: Defective GNE causes sialuria, NK and IBM2
Metabolism of proteins: Sialic acid metabolism
Gene Ontology:
Molecular function: N-acylmannosamine kinase activity; protein binding; UDP-N-acetylglucosamine 2-epimerase activity; hydrolase activity, hydrolyzing O-glycosyl compounds
Biological process: CMP-N-acetylneuraminate biosynthetic process; N-acetylneuraminate biosynthetic process; N-acetylglucosamine biosynthetic process; N-acetylneuraminate metabolic process; UDP-N-acetylglucosamine metabolic process
Cellular component: cytosol
Genetic constraint (gnomAD): Loss-of-function variants: 31 observed, 50.97 expected, observed/expected ratio (o/e) 0.61, 90% interval 0.46 to 0.82. The synonymous counts are far from expectation, so gnomAD's model fits this gene poorly and the ratio says little. Missense variants: 539 observed, 860.37 expected, observed/expected ratio (o/e) 0.63, 90% interval 0.58 to 0.67. Synonymous variants: 241 observed, 312.83 expected, observed/expected ratio (o/e) 0.77, 90% interval 0.69 to 0.86.
Gene-disease validity (ClinGen):
ClinGen rates the evidence that GNE causes each of these diseases.
macrothrombocytopenia, isolated (autosomal recessive): Definitive.
Homologues: Orthologues: chimpanzee GNE (100% identical), macaque GNE (99% identical), rabbit GNE (99% identical), dog GNE (99% identical), pig GNE (99% identical), mouse Gne (99% identical), rat Gne (99% identical), guinea pig GNE (93% identical), tropical clawed frog gne (87% identical), zebrafish gne (81% identical).
Diseases named in the same sentence as GNE in open-access papers:
GNE is named in the same sentence as 60 diseases in open-access papers, as found by Europe PMC text mining. Sharing a sentence is not in itself a finding about the gene and the disease. The quoted sentences say what the papers report.
GNE myopathy (35 papers, 2009 to 2026). "In this study, we evaluated two novel analogs of hydroxyethylamine & phthalimide (LTC-181 and LTC-1717) for their potential effect on the epimerase activity of mutant GNE proteins associated with GNE myopathy." (PMID 41339784, 2025). "Contrary to this, variant c.2179G > A (p.Val727Met) in the GNE gene was observed in all patients with GNE myopathy (OMIM#605820) in the present study in compound heterozygous state." (PMID 39138584, 2024). "Dysfunction within protein sialyation has been associated with the neuromuscular condition called GNE myopathy, caused by a mutation to GNE." (PMID 39456185, 2024). "GNE myopathy (GM) is a rare autosomal recessive disorder caused by variants in the GNE gene and characterized by progressive distal muscle weakness and atrophy." (PMID 38496429, 2024). "In 2001 and 2002, it was reported that GNEM (Nonaka myopathy, distal myopathy with rimmed vacuoles) is associated with the GNE gene, which encoding the bifunctional enzyme, UDP-N-acetylglucosamine 2-epimerase/N-acetylmannosamine kinase (GNE)." (PMID 39722797, 2024). "GNE myopathy (GM) (OMIM: 605820) also known as Nonaka myopathy (NM) or hereditary inclusion body myopathy (HIBM) is a rare autosomal recessive disorder caused by variants in the GNE gene." (PMID 38496429, 2024). "GNE myopathy (GNEM) is caused by pathogenic variants in the gene encoding UDP-N-acetylglucosamine 2-epimerase/N-acetylmannosamine kinase (GNE)." (PMID 38069329, 2023). "GNE myopathy is a distal myopathy caused by biallelic variants in GNE, which encodes a protein involved in sialic acid biosynthesis." (PMID 36526893, 2022). "GNE mutations cause GNE myopathy such as hereditary inclusion body myopathy and distal myopathy with rimmed vacuoles, and O-GlcNAcylation of GNE at Thr743 cooperates with the phosphorylation at the same site to affect its efficiency and activity of GNE." (PMID 36295790, 2022). "GNE Myopathy is an adult onset, progressive neuromuscular disease caused by recessive mutations in the GNE gene." (PMID 36353515, 2022). "GNE Myopathy is a rare, recessively inherited neuromuscular worldwide disorder, caused by a spectrum of bi-allelic mutations in the human GNE gene." (PMID 36353515, 2022). "In the future, the degree of mitochondrial changes in muscle cells of patients with different GNE mutations should be investigated as a potential cause of different phenotypes of GNE myopathy." (PMID 35904705, 2022). "GNE myopathy is a heterogeneous group of ultrarare neuromuscular disorders caused by mutations in the GNE gene." (PMID 34676965, 2021). "In this study, we described the clinicopathological and genetic profiles of ten Chinese patients with GNE myopathy, among which five novel mutations were found, broadening the mutation spectrum of the GNE gene." (PMID 34676965, 2021). "Biallelic variants in GNE are associated with GNE myopathy and causative variants are known to be located in both the epimerase and kinase domains of the GNE enzyme." (PMID 34858435, 2021). "To date, more than 201 GNE mutations associated with GNE myopathy have been reported, with missense mutations making up a clear majority." (PMID 34676965, 2021). "GNE myopathy (also known as distal myopathy with rimmed vacuoles or hereditary inclusion body myopathy) is caused by mutations in the GNE gene." (PMID 33031330, 2020). "Identification of mutations in both alleles of the GNE gene is critical for diagnostic confirmation of GNE myopathy." (PMID 29305133, 2018). "GNE myopathy is a rare distal myopathy, caused by mutations in the GNE gene, affecting sialic acid synthesis." (PMID 29305133, 2018). "Identifying biallelic mutations by sequencing of the GNE gene confirms the diagnosis of GNE myopathy." (PMID 28717665, 2017). "In humans, >100 mutations in GNE are linked to GNE myopathy, a rare disease of aging that is inherited in an autosomal recessive manner." (PMID 28424265, 2017).
GNE myopathy (continued). "It is well known that the cause of GNE myopathy is a mutation in the GNE gene that produces a decrease in the sialic acid content in skeletal muscle cells." (PMID 26968811, 2016). "GNE myopathy is caused by mutations in the GNE gene encoding a bifunctional enzyme [uridine diphosphate-N-acetylglucosamine (UDP-GlcNAc) 2-epimerase and N-acetylmannosamine kinase] that catalyzes two rate-limiting reactions in cytosolic sialic acid synthesis." (PMID 25303967, 2014). "GNE myopathy is a rare genetic neuromuscular disorder caused by mutations in the GNE gene." (PMID 41597273, 2026). "GNE myopathy (GNEM) is caused by bi-allelic variants in the UDP-N-acetylglucosamine 2-epimerase (UDP-GlcNAc 2-epimerase)/N-acetylmannosamine kinase (ManNAc kinase) gene (GNE), clinically resulting in the loss of ambulation within 10–20 years from the onset of the initial symptoms." (PMID 39519852, 2024). "GNE myopathy is caused by GNE mutations, which decrease SA content in skeletal muscle cells." (PMID 35904705, 2022). "GNE myopathy is a rare distal myopathy caused by mutations of the GNE gene." (PMID 35590323, 2022). "The GNE gene and GNE Myopathy-associated mutations have been studied for two decades, but the mechanism in which GNE mutations lead to the development of a muscle pathology remains unclear." (PMID 36353515, 2022). "In mice, the GNE protein is expressed and plays an important role in an early embryonic stage, and Gne−/− is lethal to mice, which is consistent with the clinical lack of biallelic null mutations and only ‘mildly deleterious’ mutations reported in GNE myopathy patients." (PMID 34676965, 2021). "Additional work is needed to determine whether this previously unrecognized role of GNE in regulating N-linked glycan structure contributes to phenotypes observed in GNE myopathies." (PMID 28424265, 2017). "Therefore it is critical to develop novel model systems to comprehensively examine the functions of the GNE protein in muscle, which could eventually explain the pathophysiological downstream defects caused by GNE mutations in GNE Myopathy." (PMID 36353515, 2022). "GNE myopathy (GNE-M), which was formerly known as Nonaka myopathy (NM), is an ultra-rare autosomal recessive distal myopathy caused by a biallelic variant in UDP-N-acetylglucosamine 2-epomerase/N-acetylmannosamine kinase (GNE)." (PMID 40687627, 2025). "GNE myopathy (OMIM 605820), also known as distal myopathy with rimmed vacuoles (DMRV), is a rare distal myopathy caused by mutations of the GNE gene in an autosomal recessive inheritance pattern." (PMID 35590323, 2022). "UDP-N-acetylglucosamine-2-epimerase/N-acetylmannosamine kinase (GNE) myopathy (GNEM) is an autosomal recessive distal myopathy with rimmed vacuoles typically manifesting in late adolescence/early adulthood." (PMID 36085325, 2022). "In patients with GNE myopathy, genetic alterations in either the epimerase or kinase enzymatic domains of GNE decrease both enzyme activities independently of the domain affected, as it is typical for bifunctional enzymes." (PMID 34257421, 2021). "In muscles of GNE myopathy patients, immunohistochemistry allowed the identification of the GNE protein in sarcoplasm and specifically in myonuclei as well as within rimmed vacuoles." (PMID 29720219, 2018). "Because GNE myopathy is an autosomal recessive disease, we selected a cell line that lacks endogenous GNE activity." (PMID 28424265, 2017). "GNE myopathy (GNEM), also known as hereditary inclusion body myopathy (HIBM), is a late- onset, progressive myopathy caused by mutations in the GNE gene encoding the enzyme responsible for the first regulated step in the biosynthesis of sialic acid (SA)." (PMID 28267778, 2017). "GNE myopathy (GNEM) is a late-onset muscle atrophy, caused by mutations in the gene for the key enzyme of sialic acid biosynthesis, UDP-N-acetylglucosamine 2-epimerase/N-acetylmannosamine kinase (GNE)." (PMID 38224318, 2024).
GNE myopathy (continued). "GNE myopathy (GNEM; OMIM 605820) is an autosomal-recessive disease, caused by mutations in the gene encoding the bi-functional UDP-N-acetylglucosamine 2-epimerase/N-acetylmannosamine kinase (GNE), which is the key enzyme of the sialic acid biosynthesis." (PMID 36979358, 2023). "GNE myopathy (GNEM) is a rare hereditary disease, but at the same time, it is the most common distal myopathy in several countries due to a founder effect of some pathogenic variants in the GNE gene." (PMID 36360228, 2022). "Mutations of the GNE protein cause sialurea or autosomal recessive inclusion body myopathy/Nonaka myopathy." (PMID 19841673, 2009). "Based on the effect of these HEA compounds on GNE enzyme activity and cellular functions that enhance cytoskeletal stability and lessen muscle wasting, we propose to explore them as therapeutic lead molecules for the treatment of GNE Myopathy, a rare neuromuscular disorder." (PMID 41339784, 2025). "Additionally, GNE myopathy, an adult‐onset disorder caused by recessive mutations in the UDP‐N‐acetylglucosamine‐2‐epimerase/N‐acetylmannosamine‐kinase (GNE) gene, has shown potential for AAV‐delivered GNE gene replacement in cellular and murine models." (PMID 39949979, 2025). "However, marked GNE deficiency has not been observed in GNE Myopathy patients." (PMID 36353515, 2022). "GNE myopathy, also known as Nonaka myopathy or IBM 2, is a recessive disorder and a result of mutations in the GNE gene that encodes the bifunctional UDP-N-acetylglucosamine-2-epimerase/N-acetylmannosamine kinase on chromosome 9p13." (PMID 36399165, 2023).
distal myopathy (14 papers, 2015 to 2025). Distal myopathy refers to a group of muscle diseases which share the clinical pattern of predominant weakness and atrophy beginning in the feet and/or hands. "GNE-myopathy (GNEM) is a rare autosomal recessive muscle disease that belongs to the group of distal myopathies with adult-onset initial involvement of anterior leg compartment and caused by biallelic variants in the GNE gene." (PMID 39722797, 2024). "The compound heterozygous missense p.Gly142Arg and p.Phe315Ser variants of the GNE gene were found in patient 3 of family B. The novel compound heterozygous variants cosegregated with the distal myopathy phenotype in the family." (PMID 35590323, 2022). "GNE mutations are also associated with distal myopathies with distal weakness but longer duration of disease and myopathic findings on electrodiagnostic studies." (PMID 34946884, 2021).
Thrombocytopenia (8 papers, 2020 to 2025). A reduction in the number of circulating thrombocytes. "It has been hypothesized that mutations in GNE cause thrombocytopenia only when co-segregated with other genetic factors, such as ANKRD18A, FRMPD1, FLNB, and PRKACG, which have been described in other cases." (PMID 36982178, 2023). "To date, new GNE variants associated with severe thrombocytopenia are found." (PMID 35572556, 2022). "These two GNE mutations may help in the diagnosis and management of thrombocytopenia diagnosed in neonates." (PMID 33198675, 2020). "Here we report a case of twins with severe inherited thrombocytopenia presented in the neonatal period who were shown to be compound heterozygotes for 2 UDP-N-acetylglucosamine 2-epimerase (GNE) gene mutations, c.1351C > T and c.1330G > T, of which c.1330G > T is a novel mutation." (PMID 33198675, 2020). "Therefore, the twins were diagnosed with congenital thrombocytopenia associated with GNE mutations." (PMID 33198675, 2020). "The phenotype of the patients with genetic alterations in GNE, SLC35A1, GALE and B4GALT is consistent with syndromic manifestations, severe inherited thrombocytopenia, and hemorrhagic complications." (PMID 36982178, 2023). "Notably, thrombocytopenia has also been described in various other types of CDG, including ALG1-, ALG8-, GALE-, GNE-, MPI-, PMM2-, and B4GALT1-CDG." (PMID 40613041, 2025).
hereditary inclusion-body myopathy (6 papers, 2008 to 2022). "Hereditary inclusion body myopathy (HIBM) is a rare neuromuscular disorder caused by mutations in GNE, the key enzyme in the biosynthetic pathway of sialic acid." (PMID 18560563, 2008). "In the context of the recessive disease Hereditary Inclusion Body Myopathy (HIBM), caused by missense mutations in GNE, we were interested in elucidating possible roles of GNE specifically in skeletal muscle." (PMID 21731727, 2011).
sialuria (4 papers, 2008 to 2022). "French type sialuria is caused by mutations in the allosteric binding site of GNE, thereby resulting in increased production of NeuNAc and CMP-NeuNAc." (PMID 34939087, 2022). "Sialuria is a rare genetic disorder caused by mutation in the allosteric site of GNE leading to failure of feedback mechanism of GNE enzyme, resulting in excess excretion of sialic acid in the urine." (PMID 33816461, 2021). "It is likely related to the stringent feedback regulation of GNE activity, and clearly explains why single mutations at Arg263 or Arg266 can cause sialuria." (PMID 26980148, 2016). "Sialuria is a human disease caused by point mutations in the CMP-sialic acid binding site of GNE, leading to a loss of feed-back inhibition and mass production of sialic acids." (PMID 19787087, 2008). "One could also consider use of the sialuria variant of GNE for expression in HIBM patient’s cells to rescue the long-time hyposialylation of the tissue, of course taking into account the side effects of sialic acid overproduction observed in sialuria patients." (PMID 19787087, 2008).
muscle disorder (3 papers, 2009 to 2024). "Hereditary IBM (hIBM) is a an autosomal recessive muscle disorder tied to a mutation in the UDP-N-acetylglucosamine 2-epimerase/N-acetylmannosamine kinase (GNE) that codes for a rate-limiting enzyme in the sialic acid biosynthetic pathway." (PMID 23758833, 2013). "Hereditary inclusion body myopathy-2 (HIBM2) is an adult-onset, muscular disease caused by mutations in the GNE gene." (PMID 19838336, 2009).
prostate carcinoma (3 papers, 2022 to 2025). A carcinoma that arises from epithelial cells of the prostate gland. "Further studies showed that ELVOL1, PDCD10, and GNE proteins were also significantly over-expressed in prostate cancer." (PMID 35706452, 2022). "Although both CBPD-409 and GNE-049 triggered a similar decrease in overall abundance of H3K27ac histone modifications, motif analyses revealed that CBPD-409 preferentially abolished the H3K27ac peaks at binding sites of prostate cancer-specific TFs." (PMID 41044247, 2025).
lymphoma (2 papers, 2015 to 2019). A malignant (clonal) proliferation of B- lymphocytes or T- lymphocytes which involves the lymph nodes, bone marrow and/or extranodal sites. "Inhibition of ST6Gal1 or GNE activity in lymphoma cells may cause apoptosis, thereby reducing tumor mass or metastatic nodules and enhancing the effects of anticancer drugs." (PMID 31317621, 2019). "Therefore, in addition to ST6Gal1, GNE is also a candidate target for lymphoma therapy, especially for the prevention of metastasis." (PMID 31317621, 2019). "We speculate that since removal of cell surface sialic acid by knockdown of GNE induces HBL‐8 cell death, oncolysis of lymphoma cells may be induced by neuraminidase treatment or knockdown of ST6Gal1 or GNE." (PMID 31317621, 2019).
Macrothrombocytopenia (2 papers, 2019 to 2021). "We report two previously undescribed variants in GNE causing severe congenital macrothrombocytopenia in a compound heterozygous state, as a consequence of decreased platelet sialylation." (PMID 34858435, 2021). "The present report shows evidence of compound heterozygous variants in GNE (p.Ile139Argfs*4 and p.Arg451Gln) causing constitutional macrothrombocytopenia, as a result of decreased platelet sialylation." (PMID 34858435, 2021).
pancreatic carcinoma (2 papers, 2017 to 2021). "GNE dysregulation occurred predominantly in pancreatic cancer but also in other malignancies." (PMID 28009993, 2017).
Becker muscular dystrophy (1 paper, 2022). Becker muscular dystrophy (BMD) is a neuromuscular disease characterized by progressive muscle wasting and weakness due to degeneration of skeletal, smooth and cardiac muscle. "As a non-invasive quantitative MRI technique, T1-mapping has been increasingly applied to monitor chronic fatty degenerations of lower limb muscles within the course of NMDs; e.g. Becker muscular dystrophy (BMD) or UDP-N-acetylglucosamine 2-epimerase/N-acetylmannosamine kinase (GNE) myopathy." (PMID 35842609, 2022).
cerebral palsy (1 paper, 2019). A group of disorders affecting the development of movement and posture, often accompanied by disturbances of sensation, perception, cognition, and behavior. "For example, the stiffness of cerebral palsy and Duchenne muscular dystrophy were increased, while decreased in GNE (UDP-N-acetylglucosamine 2- epimerase/N-acetylmannosamine kinase)." (PMID 31781292, 2019).